PGF (placental growth factor)
Description:
Growth factor active in angiogenesis and endothelial cell growth, stimulating their proliferation and migration. It binds to the receptor FLT1/VEGFR-1. Isoform PlGF-2 binds NRP1/neuropilin-1 and NRP2/neuropilin-2 in a heparin-dependent manner. Also promotes cell tumor growth.
Synonyms: PlGF; PGFL; PlGF-2; SHGC-10760; D12S1900; PIGF
Tractability: Small molecule: a structure with a bound ligand is known. Antibody: a drug acting on it is in phase 2 or 3 trials; its Gene Ontology location is reachable by antibodies, with high confidence; UniProt places it where antibodies can reach, with medium confidence; UniProt predicts a signal peptide or a membrane-spanning region. PROTAC: a small molecule that binds it is known. Other modalities: an approved drug acts on it.
Target class: Secreted protein
Gene: Protein-coding gene on chromosome 14 (74,941,830 to 74,955,626, reverse strand). Ensembl gene ENSG00000119630.
Subcellular location: Secreted
Subcellular location (Human Protein Atlas): Nucleoplasm; Cytosol; Mitochondria; Predicted to be secreted
Pathways (Reactome):
Signal Transduction: VEGF binds to VEGFR leading to receptor dimerization; VEGF ligand-receptor interactions
Gene Ontology:
Molecular function: growth factor activity; protein binding; chemoattractant activity; vascular endothelial growth factor receptor binding; receptor ligand activity
Biological process: positive regulation of cell population proliferation; cell-cell signaling; induction of positive chemotaxis; positive regulation of mast cell chemotaxis; response to hypoxia; signal transduction; sprouting angiogenesis; vascular endothelial growth factor receptor signaling pathway; vascular endothelial growth factor signaling pathway; positive chemotaxis
Cellular component: extracellular region; membrane
Genetic constraint (gnomAD): Loss-of-function variants: 9 observed, 20.05 expected, observed/expected ratio (o/e) 0.45, 90% interval 0.27 to 0.78. The upper end of that interval is the gene's LOEUF score, 0.78, which puts it in group 3 of 6, group 1 being the genes least tolerant of losing a copy. Missense variants: 209 observed, 204.79 expected, observed/expected ratio (o/e) 1.02, 90% interval 0.91 to 1.14. Synonymous variants: 99 observed, 86.41 expected, observed/expected ratio (o/e) 1.15, 90% interval 0.97 to 1.35.
Homologues: Orthologues: macaque PGF (98% identical), pig PGF (94% identical), rabbit PGF (90% identical), chimpanzee PGF (86% identical), dog PGF (86% identical), guinea pig PGF (75% identical), mouse Pgf (59% identical), rat Pgf (56% identical), zebrafish pgfb (49% identical). Paralogues in human: VEGFA (43% identical), VEGFC (29% identical), VEGFD (29% identical), VEGFB (27% identical).
Diseases named in the same sentence as PGF in open-access papers:
PGF is named in the same sentence as 339 diseases in open-access papers, as found by Europe PMC text mining. Sharing a sentence is not in itself a finding about the gene and the disease. The quoted sentences say what the papers report.
preeclampsia (546 papers, 2008 to 2026). Preeclampsia is a hypertensive disorder of pregnancy that is characterized by new-onset hypertension with proteinuria presenting after 20 weeks of gestation, and depending on mild or severe forms may initially present with severe headache, visual disturbances, and hyperreflexia. "At 36 weeks, the ratio of soluble fms-like tyrosine kinase 1 (sFlt-1) to placental growth factor (PlGF) showed an increased risk of developing preeclampsia in the following 4 weeks." (PMID 40734702, 2025). "Early preeclampsia is often linked to placental dysfunction, with placental growth factor (PLGF) implicated in endothelial dysfunction in affected individuals." (PMID 41473191, 2025). "Key predictors included mean arterial pressure, prior preeclampsia, and the biomarkers placental growth factor (PlGF) and pregnancy-associated plasma protein A (PAPP-A)." (PMID 40510095, 2025). "Maternal platelet activation (P-selectin positive platelets) was linked with disease severity (sFlt-1/placental growth factor) and maternal plasma IL-1β and sVCAM-1 only in late-onset preeclampsia." (PMID 40746439, 2025). "PlGF (placental growth factor) concentrations are lower in preeclampsia, a major cause of maternal death; testing improves diagnosis and outcomes." (PMID 40762064, 2025). "A hallmark of placentas from preeclampsia is reduced secretion of placental growth factor, which is a pro-angiogenic molecule important for maintaining endothelial integrity." (PMID 39758342, 2024). "Changes in soluble fms-like tyrosine kinase-1 (sFlt-1) and placental growth factor (PlGF) levels were measured between 11–13 g.w. before the onset of preeclampsia and its associated complications." (PMID 39769260, 2024). "Preeclampsia is caused by placental hypoxia and systemic inflammation and is associated with reduced placental growth factor (PlGF) and endothelial nitric oxide synthase (eNOS) levels." (PMID 38825645, 2024). "This study successfully designs and evaluates novel aptamers with high specificity and affinity for Vascular Endothelial Growth Factor (VEGF) and Placental Growth Factor (PlGF), biomarkers closely associated with preeclampsia." (PMID 39334133, 2024). "The sFlt-1/PlGF (fms-like tyrosine kinase-1/placental growth factor) ratio has demonstrated robust diagnostic value for preeclampsia." (PMID 38533029, 2024). "Salivary uric acid and placental growth factor (PlGF) have been investigated for their association with the risk of preeclampsia." (PMID 37342498, 2023). "Many studies indicate that statins also raise the levels of PlGF (placental growth factor); in this way, they reduce the levels of sFlt-1, thus helping to fight against the antiangiogenic factors that cause preeclampsia." (PMID 37762960, 2023). "Patients enrolled in the intervention phase had sFlt-1 (soluble fms-like tyrosine kinase-1)/PlGF (placental growth factor) ratio and preeclampsia integrated estimate of risk assessments performed." (PMID 37431663, 2023). "Preeclampsia is associated with placental ischemia, which consequently reduces the levels of placental growth factor, with increased coagulopathy resulting from the activation of the fibrinolytic system, platelet activation, and a decrease in platelet counts." (PMID 35490217, 2022). "Placental growth factor (PGF), a protein encoded by the PGF gene, can help predict, diagnose, and treat preeclampsia." (PMID 36407236, 2022). "Changing expression patterns of PGF isoforms, previously shown to associate with preeclampsia, identified six isoforms of PGF, three of which were protein coding and three of which that were non-coding with retained introns." (PMID 35562897, 2022). "Preeclampsia is associated with dysregulation of angiogenic factors such as soluble fms-like tyrosine 1 (sFlt-1) and placental growth factor (PlGF)." (PMID 33594274, 2021).
preeclampsia (continued). "Aspirin, known to increase the serum concentration of placental growth factor in pregnant women, prevents the development of preterm preeclampsia in women who are at a high risk of developing preeclampsia and take aspirin from the first trimester." (PMID 33670947, 2021). "An imbalance of circulating maternal levels of soluble fms-like tyrosine kinase 1 (sFlt-1) and placental growth factor (PlGF) is associated with preeclampsia development." (PMID 34497833, 2021). "We next analyzed serum levels of placental growth factor (PlGF) and soluble fms-like tyrosine kinase-1 (sFlt-1), which are consistently altered in preeclampsia (reduced PlGF, elevated sFlt-1) and reflective of underlying placental dysfunction." (PMID 33301424, 2021). "An increase in the concentrations of maternally circulating endoglin and sFlt1, and a subsequent decrease in placental growth factor (PlGF) signaling were identified as the major causal factors for the development of preeclampsia." (PMID 34992598, 2021). "Prospective nested qualitative cohort study embedded within a national, multi‐site randomized controlled trial of a diagnostic test for preeclampsia: Placental Growth Factor." (PMID 31578808, 2020). "Potential biomarkers for first trimester preeclampsia screening include serum placental growth factor (PlGF), serum pregnancy-associated plasma protein A (PAPP-A), mean arterial pressure (MAP) and uterine artery pulsatility index (UTPI)." (PMID 32266293, 2020). "Quantification of the soluble fms-like tyrosine kinase-1 (sFlt-1) and placental growth factor (PlGF) ratio has shown a diagnostic value in the second and third trimesters of pregnancy, in particular in ruling out preeclampsia within one week." (PMID 31485276, 2019). "Preeclampsia is associated with placental ischemia, which consequently reduces the placental growth factor (PIGF) level, with increased coagulopathy resulting from activation of the fibrinolytic system, platelet activation, and a decrease in platelet count." (PMID 31805880, 2019). "For example, O’Gorman and colleagues reported an AUC of 0.95 for preeclampsia before 32 weeks and an AUC of 0.87 for any preeclampsia before 37 weeks using 11 to 13 week placental growth factor (PLGF) and pregnancy-associated plasma protein A (PAPP-A)." (PMID 29795450, 2018). "An sFlt-1 (soluble fms-like tyrosine kinase 1) to PlGF (placental growth factor) ratio >38 at 28 weeks of gestational age identified women with a high risk (>30%) of subsequently delivering preterm with preeclampsia." (PMID 28167687, 2017). "It has been shown that sFlt-1 debris from preeclampsia placenta bind to vascular endothelial growth factors and placental growth factor and deprived the essential survival factors, causing the clinical feature of preeclampsia." (PMID 25392996, 2014). "Our primary objective was to establish a cutoff value for the soluble fms-like tyrosine kinase 1(sFlt-1)/placental growth factor (PlGF) ratio measured using the Elecsys assay to predict late-onset preeclampsia in low-risk pregnancies." (PMID 24444293, 2014). "A possible physiological pathway involves abnormal increases in soluble fms-like tyrosine kinase-1 (sFlt-1) and soluble endoglin (sEng), accompanied by a decrease in placental growth factor (PlGF), which have been implicated in the pathogenesis of preeclampsia." (PMID 41115997, 2026). "Preeclampsia, a severe pregnancy complication linked to defective placentation, poses significant maternal risks and is characterized by dysregulated angiogenic factors, including placental growth factor (PlGF) and soluble fms-like tyrosine kinase-1 (sFlt-1)." (PMID 39579213, 2024). "Interestingly, reduced placental growth factor in preeclampsia is associated with nuclear localization of ATF4 and ATF6β (but not ATF6⍺ or XBP1) in the STB layer." (PMID 39758342, 2024).
preeclampsia (continued). "Importantly, the ratio of soluble fms-like tyrosine kinase 1 (sFlt) to placental growth factor (PlGF) was recently approved by the FDA for clinical utilization as a predictor of preeclampsia risk over either biomarker individually." (PMID 38255935, 2024). "Maternal characteristics (such as maternal age, height, pre-pregnancy weight), past medical history, mean arterial pressure, uterine artery pulsatility index, pregnancy-associated plasma protein A, and placental growth factor were collected as the covariates for the preeclampsia prediction model." (PMID 38919479, 2024). "SARS-CoV-2, which modifies placental growth factor (PlGF) and excess placental soluble fms-like tyrosine kinase 1 (sFlt1) in infected placentas, may be the cause of preeclampsia." (PMID 37090385, 2023). "Interestingly, this UPR arm has also been linked with early-onset of preeclampsia and uterine growth restriction, through the down-regulation of placental growth factor (PlGF), an important regulator of angiogenesis." (PMID 32357311, 2020). "We assessed whether placental growth factor (PlGF), a biomarker associated with preeclampsia risk, adds incremental value to the fullPIERS model." (PMID 33153436, 2020). "Maternal concentrations of the placenta-associated proteins placental growth factor (PlGF) and soluble fms-like tyrosine kinase-1 (sFlt-1) have been identified as predictors for preeclampsia and fetal growth restriction, both syndromes of placental dysfunction." (PMID 33079955, 2020). "Maternal serum analytes such as pregnancy-associated plasma protein-A (PAPP-A) and placental growth factor (PlGF), which have already been used in the screening of preeclampsia and been proven to be associated with APOs, were also available in the first trimester." (PMID 32050927, 2020). "Preeclampsia is associated with disordered release of angiogenesis-related factors into the maternal circulation – reduced pro-angiogenic placental growth factor (PlGF) and increased anti-angiogenic soluble fms-like tyrosine kinase 1 (sFlt-1)." (PMID 30170567, 2018). "Preeclampsia is associated with an altered maternal pattern of circulating placentally derived proteins regulating angiogenesis, such as sFlt-1 (soluble fms-like tyrosine kinase 1) and PlGF (placental growth factor)." (PMID 28167687, 2017). "An imbalance of circulating angiogenic factors, specifically an increase in anti-angiogenic proteins, sFlt1 and sEng, and a decrease in the pro-angiogenic protein, placental growth factor (PlGF), has been proposed as causing some of the clinical manifestations of preeclampsia." (PMID 20967275, 2010). "Risk for preterm preeclampsia was assessed using the Fetal Medicine Foundation algorithm, which includes maternal risk factors, uterine artery Doppler, mean arterial pressure and serum markers (Placental growth factor, PlGF and Pregnancy-associated plasma protein-A, PAPP-A)." (PMID 39815166, 2025). "According to the fetal medicine foundation recommendation, attempts to predict preeclampsia are made by using a combination of parameters, such as maternal risk factors, the uterine artery Doppler pulsatility index, mean arterial pressure, and serum placental growth factor." (PMID 39590594, 2024). "The soluble fms-like tyrosine kinase-1-to-placental growth factor (sFlt-1/PlGF) ratio has emerged as a promising biomarker for preeclampsia; however, its prognostic value for maternal and neonatal outcomes remains incompletely defined." (PMID 41827409, 2026). "Preeclampsia is characterized by an imbalance between pro-angiogenic factors (such as placental growth factor, PlGF) and anti-angiogenic factors (such as soluble fms-like tyrosine kinase-1, sFlt-1)." (PMID 40573136, 2025). "On this basis, prenatal screening markers combined with serum PLGF in early pregnancy were selected to observe the predictive value of prenatal screening markers combined with serum placental growth factor (PLGF) in early pregnancy for preeclampsia (PE)." (PMID 39926691, 2025).
preeclampsia (continued). "Proteins like soluble tyrosine kinase-1 (sFlt-1) and placental growth factor (PlGF) are considered possible biomarkers to predict preterm preeclampsia." (PMID 40694862, 2025). "Anti‐angiogenic factor soluble fms‐like tyrosine kinase 1 (sFlt‐1) and pro‐angiogenic factor placental growth factor (PlGF) are routinely measured in plasma and serum of individuals for prediction or primary prevention of preeclampsia worldwide." (PMID 40746214, 2025). "More recently, PAPP‐A has been investigated for its potential use in screening for preeclampsia; however, other maternal serum proteins such as placental growth factor (PlGF) are the preferred biochemical marker." (PMID 40128623, 2025). "This should be evaluated in prospective trials and is the subject of the current PAPAGAIO (Preterm preeclampsia: Placental Growth factor for reduction of Adverse Outcomes) trial in Brazil, India, and Sierra Leone using these POC tests." (PMID 40762064, 2025). "In addition, angiogenesis-related factors —highlighting placental growth factor (PlGF), soluble fms-like tyrosine kinase-1 (sFlt-1), and human chorionic gonadotropin (hCG)—have shown utility in identifying pregnancies at risk for preeclampsia and other placental syndromes." (PMID 40649890, 2025). "Another suggested biomarker, the ratio of soluble fms-like tyrosine kinase 1 (sFlt-1) to placental growth factor (PlGF), has been reported as elevated in pregnant women before clinical onset of preeclampsia and eclampsia." (PMID 40369503, 2025). "Our results confirmed the relationship between placental growth factor (PlGF) levels and the incidence of preeclampsia." (PMID 41473191, 2025). "For example, placental growth factor (PGF) is markedly decreased in preeclampsia compared to normal pregnancy." (PMID 40827175, 2025). "As counterparts, soluble fms-like tyrosine kinase (sFlt-1) and placental growth factor (PlGF) are integral to the angiogenic profile of preeclampsia and are effective indicators of placental dysfunction." (PMID 40149572, 2025). "Serum soluble fms-like-tyrosine-kinase-1 (sFlt-1) to placental-growth-factor (PlGF) ratio (to predict preeclampsia) was used as an early biomarker of placental dysfunction." (PMID 41293171, 2025). "In fact, the involvement of H2S production on plasma levels of sFLT1, PGF, and other molecules related to preeclampsia has been demonstrated." (PMID 38276547, 2024). "Soluble fms-like tyrosine kinase-1 (sFlt-1) is increased, and placental growth factor (PlGF) decreased, in the circulation of women with preeclampsia." (PMID 38955620, 2024). "Chemerin was determined in a prospective cohort study in women suspected of preeclampsia and evaluated as a predictor versus the sFlt-1 (soluble fms-like tyrosine kinase-1)/PlGF (placental growth factor) ratio." (PMID 38361240, 2024). "A novel first-trimester screening algorithm, validated to predict preterm preeclampsia, incorporates mean arterial blood pressure, Doppler ultrasound-measured maternal uterine artery resistance, and Placental Growth Factor (PlGF) levels." (PMID 38424566, 2024). "Mutations in the FOXD1 gene are also related to RIF, intrauterine growth restriction, and preeclampsia through the regulation of angiogenesis and vasoconstriction-related genes, including complement component 3 (C3) and placental growth factor (PlGF)." (PMID 39498089, 2024). "Among these biomarkers, Vascular Endothelial Growth Factor (VEGF) and Placental Growth Factor (PlGF) proteins are prominent due to their roles in the angiogenic imbalance characteristic of preeclampsia." (PMID 39334133, 2024). "The ratio of maternal angiogenic proteins including soluble Fms‐like tyrosine kinase 1(sFlt‐1) and placental growth factor (PlGF) provides a measure of anti‐angiogenesis, and is measured in the mid‐to‐late 2nd trimester to predict preeclampsia." (PMID 38193120, 2024).